ENSG00000238832
Synonyms: LOC124901856
Gene: Small nucleolar RNA gene on chromosome 7 (107,603,363 to 107,603,507, forward strand). Ensembl gene ENSG00000238832.
Gene Ontology:
Biological process: RNA processing
Cellular component: nucleolus
Homologues: Paralogues in human: SCARNA18B (74% identical), SCARNA18 (74% identical).